MCM4 (minichromosome maintenance complex component 4)
Diseases named in the same sentence as MCM4 in open-access papers (continued):
Sharing a sentence is not in itself a finding about the gene and the disease.
cancer (continued). "The present study demonstrated that MCM4 expression was associated with high Ki-67 labeling index in both UTUC and BC-TCGA data, which was consistent with previous studies showing MCM4 to be a proliferation marker in several cancers." (PMID 37737200, 2023). "Oncomine database compared the transcription level of MCM4 in cancer and normal samples." (PMID 35719366, 2022). "Some reports of cancers have been made within the MCM4 cohort, but all of them could be attributable to viral transformation secondary to NK cell depletion." (PMID 33477564, 2021). "This explains why three out of four Irish CNKD children did not develop cancer despite having the same MCM4 mutations." (PMID 31379882, 2019). "MCM2-7 were all upregulated in carcinoma tissue in our data, and MCM3, MCM4, and MCM6 were associated with differential miRNA expression, including hsa-miR-106b-5p, hsa-miR-17-5p, hsa-miR-19b-3p, hsa-miR-20a-5p, hsa-miR-20b-5p, hsa-miR-25-3p, and hsa-miR-93-5p." (PMID 29725503, 2018). "MCM4 expression was also increased in stage T3 carcinoma when compared with stage T1 carcinoma." (PMID 27476776, 2016). "In addition, we demonstrated the effects of heliquinomycin, an inhibitor of MCM4/6/7-dependent DNA helicase activity, on the growth of cancer cells." (PMID 21619671, 2011). "Furthermore, an optimal dose of heliquinomycin, a specific inhibitor of MCM4/6/7-dependent DNA helicase activity, more effectively inhibited the growth of cancer cell lines than that of HFL-1 cell line." (PMID 21619671, 2011). "However, targeting MCM4 for cancer therapy presents both promise and significant challenges." (PMID 40959096, 2025). "However, little is known about the role and mechanism of MCM4 in cancers." (PMID 34859821, 2021). "Thus, Cy induced down regulation in Ras, LMO2, MCM4 and MCM7 genes might shed light on the mechanisms underlying the anti-cancer effects of Cy." (PMID 24466173, 2014). "Remarkably, the group of cancer-related proteins,i.e., CEACAM1,CEACAM5, and CEACAM6 as well as the minichromosome maintenance complexcomponents MCM3, MCM4, and MCM6 showed clear protein abundance patternsrelated to the radiation response." (PMID 40574313, 2025). "PGK1 has been reported to promote cancer cell proliferation and migration in NSCLC through the downstream ERK/MCM4 pathway." (PMID 38674080, 2024). "Kaplan–Meier curves were generated to visualize the relationship between MCM4 expression and overall survival (OS) or disease-free survival (DFS) in each cancer type." (PMID 38499612, 2024). "In this analysis to discover cancer subgroups, PTDSS1, MCM4 and PRKDC genes were identified as molecular drivers belonging to the same subgroup." (PMID 37489460, 2023). "Cancers displaying unfavorable risk with high ALT (BRCA, SARC, and LUAD) may be regulated by the transcriptional factors E2F4, TFDP1, E2F1, E2F7, and SIN3A (FDR = 0.001) in the DNA repair pathway, including genes repairing DNA damage such as CENPI, CLSPN, TOPBP1, and MCM4." (PMID 32784588, 2020). "Unexpectedly, 3 of the 4 genes are from the gene list with prognostic value in > 6 cancers (YWHAB, MCM4, FBXO46)." (PMID 31387239, 2019). "Knock out mouse model studies of CHK1, MCM4, and RAD1 all show embryonic lethality in homozygous null mice and increased cancer incidence in heterozygotes, similarly to BRCA1/2, which makes them compelling and worthy of following up with functional studies." (PMID 28591191, 2017). "Of the rest, CPEB4, MCM4, RNF4, STAT2, and WEE1 were also shown to correlate with a number of cancer types." (PMID 27418131, 2016).
cancer (continued). "Two nodes, named Mcm4 and Mcm7, were upregulated in AD vs. K and in AD vs. D. These findings suggested that any gene expression level changes in module 1 could result in the dysregulation of cell cycle progression and could affect the progression of inflammation and cancer." (PMID 24743346, 2014). "We observed that MCM4 expression was not significantly elevated in several cancer types, such as KIRC and PRAD." (PMID 40959096, 2025). "The literature has demonstrated overexpression of MCM2, MCM4, and MCM6 in various cancers." (PMID 40445576, 2025). "The significance of our study lies in the fact that MCM4 has not been previously studied extensively as a potential biomarker for cancer prognosis, diagnosis and drug sensitivity." (PMID 38499612, 2024). "Despite the existing research on this topic, a comprehensive analysis of MCM4 across various cancer types has been lacking." (PMID 38499612, 2024). "Furthermore, we used the GSCALite database and assessed the correlation of drug sensitivity with MCM4 according to the Cancer Therapy Response Portal (CTRP) and genomics of drug sensitivity in cancer (GDSC)." (PMID 36291859, 2022). "Moreover, some other genes including AKT, c-myc, MCM4, and EIF2S2 were also significantly elevated in cancer tissues." (PMID 36497260, 2022). "The cancers have been observed in NKD patients with GATA2 and MCM4 mutations although not in patients with IRF8, RTEL1, and FCGR3A mutations." (PMID 31379882, 2019). "And they could be regarded as indicators for certain cancer progression and prognosis.Our results also suggested that some members of MCM2-7 complex could predict PC progression (MCM4 for T stage)." (PMID 27695057, 2016). "MCM4 and MCM7 are the part of MCM protein family, which play an essential roles in initiation of DNA replication and may be pre-cancer markers." (PMID 26156831, 2015). "In addition to the genes related to the immune system, our findings also demonstrated that treatment with Cy down-regulates the expression of several genes (e.g., Ras, LMO2, MCM4 and MCM7) that are related to cancer development and cell cycle progression." (PMID 24466173, 2014). "Overexpression of AEBP1 and MCM4 for OB as well as of FABP4 for AD differentiation seem to be the most promising molecular targets which could be used for regenerative medicine, stem cell, and cancer research in the future." (PMID 35269711, 2022). "Furthermore, certain cell cycle–related proteins, including TOP2A, PCNA, MCM2, MCM4, MCM5, MCM6, and MCM7, have also been reported to facilitate cancer cell proliferation, and the enhanced expression of these cell cycle–related proteins may contribute to uncontrolled ESCC cell proliferation." (PMID 38652547, 2024). "However, to our knowledge, no studies are assessing the expression of MCM4 in pan-cancer." (PMID 35719366, 2022). "For example, in GBM individual TCGA‐06‐0648, the identified driver gene set contained both MCM4 and CXCL6, none of which were recorded as cancer genes." (PMID 37491836, 2023).
tumor (55 papers, 2007 to 2025). "Given its consistent upregulation in tumor tissues, significant correlation with advanced disease features, and strong association with poor survival outcomes, MCM4 emerges as a promising candidate for further functional investigation." (PMID 40564876, 2025). "The present data revealed that MCM4 expression was significantly associated with poor prognosis and high in tumor invasive front." (PMID 37737200, 2023). "Univariate and multivariate regression analyses demonstrated that higher expressions of LINC00460 and MCM4 were significantly associated with tumor size, lymph node metastasis, distant metastasis and TNM stage." (PMID 36291859, 2022). "We have accumulated evidence that the early-onset T-ALL phenotype in Sdl mice results from a novel allele of Mcm4 (Mcm4D573H) that in the heterozygous state promotes chromosomal abnormalities that cause highly penetrant tumor formation." (PMID 23133403, 2012). "High MCM4 expression was associated with "cold" tumor characteristics." (PMID 40959096, 2025). "Moreover, the specific mechanisms underlying the synergistic anti-tumor effects of cisplatin and MCM4 silencing require further mechanistic investigation." (PMID 39290263, 2024). "Although genetically it acts dominantly, Mcm4D573H could actually promote tumor formation in a recessive manner if loss-of-heterozygosity (LOH) or epigenetic silencing at the Mcm4 locus occurs during tumor formation." (PMID 23133403, 2012). "In our datasets GSE32863, GSE33356, and GSE27262—which contain paired tumor and adjacent normal tissues—paired t-test analysis showed that MCM4 expression was consistently elevated in tumor tissues." (PMID 40564876, 2025). "Addressing this clinical demand, we comprehensively investigated the expression of MCM4 in tumor tissue and metastatic tissue using multiple SKCM datasets." (PMID 40959096, 2025). "The analysis results showed that the expression levels of G6PD, KIF20A, NDRG1, RECQL4, and MCM4 were significantly higher in HCC tumor tissues than in normal tissues, while ADH1C was significantly downregulated in HCC tumor tissues." (PMID 41169384, 2025). "To elucidate the molecular mechanism underlying the role of MCM4 in tumor development, we constructed a PPI network and a GGI network around MCM4." (PMID 38499612, 2024). "In vitro and in vivo results confirmed that this hierarchical membrane system can effectively deliver therapeutic MCM4 siRNA and release cisplatin to inhibit tumor growth." (PMID 39290263, 2024). "Subsequently, we utilized the GEPIA2 tool to integrate tumor expression data from TCGA and identified the top 100 genes that exhibited a correlation with MCM4 expression." (PMID 38499612, 2024). "We further conducted a comparative analysis of the MCM4 phosphorylation levels in various primary tumor tissues and normal tissues utilizing the CPTAC dataset." (PMID 38499612, 2024). "In details, we found MCM4 was overexpressed in LUAD tumour samples and cells in relative to their corresponding normal controls, and high MCM4 levels led to low survival rate in patients with LUAD." (PMID 37817427, 2023). "In the present study, our immunohistochemical analysis showed that MCM4 expression was detected in 77 (62%) of 124 UTUC cases and associated with nodular/flat morphology, high tumor grade and high pathological T grade." (PMID 37737200, 2023). "The same results were observed in tumour tissues from mice models injected with LUAD cells with MCM4 knockdown." (PMID 37817427, 2023). "Here we also tested PCNA and P21 levels, and found that MCM4 silence inhibited its protein levels in tumour tissues." (PMID 37817427, 2023). "Taken together, these results suggest that MCM4 represents a useful predictor of tumor progression in UC." (PMID 37737200, 2023). "MCM4 is highly expressed in LUAD tumour samples and cells, and its upregulation is closely related to LUAD patients OS." (PMID 37817427, 2023).
tumor (continued). "Histological examination subsequently revealed the presence of high-grade UC in the bladder biopsy, and these tumor cells were also strongly immunohistochemically positive for MCM4." (PMID 37737200, 2023). "MCM4 was highly expressed in LUAD tumours and cells, and had an important effect on the overall survival." (PMID 37817427, 2023). "The MCM4 was combined with age, Clinical stage, Histologic grade, and Tumor invasion to construct a prognostic nomogram to obtain a more accurate prognostic prediction model." (PMID 35719366, 2022). "This suggests that inhibiting the expression of LINC00460 and MCM4 or upregulating the expression of mir-338-3p can both prevent tumor progression and improve the prognosis of LUAD patients." (PMID 36291859, 2022). "As a cell cycle-related regulatory gene, MCM4 can regulate tumor progression through a variety of means." (PMID 35719366, 2022). "Subsequently, the correlation between the MCM4 and tumor microenvironment (TME) and immune cell infiltration was explored." (PMID 35719366, 2022). "We then investigated the MCM4 expression profiles from our archived tumor samples, nine histology subtypes of STS in TCGA, and patient-derived tumor cell cultures (PTCCs) as a validation." (PMID 34178990, 2021). "Then, the experiment data from real-time PCR in 60 pairs of HCC tissues and adjacent tissues further demonstrated the remarkable high expression status of MCM4 in the tumor group." (PMID 34961841, 2021). "We have discovered four genes of prognostic value (CENPF, FOXM1, MCM4, and TOP2A), and further prioritized MCM4 as a key biomarker of LPS associated with tumor invasiveness (tumor stage, grade, and Ki67 labeling index) and prognostication." (PMID 34178990, 2021). "It has been reported that the MCM4 expression level in clinical samples of BC is significantly higher than that in non-tumor breast epithelium." (PMID 34475953, 2021). "This is the first report demonstrating that tumor-suppressive miR-143-5p directly regulates MCM4 in LUAD cells." (PMID 31514295, 2019). "Overexpression of MCM4 has been found previously in multiple transformed cell lines and numerous tumor types." (PMID 30107825, 2018). "Among these, MCM4, 6 and 10 show increased frequency of over expression along with advancement of tumor stages." (PMID 23874974, 2013). "High expression of PHH3 and MCM4 was correlated with high mitotic count, elevated Ki-67 expression and tumor ulceration, and increased PHH3 frequencies were associated with tumor thickness and presence of tumor necrosis." (PMID 20398247, 2010). "High expression of MCM4 was correlated with tumor ulceration (p = 0.003), high mitotic count (p = 0.002), but not with other histopathological variables." (PMID 20398247, 2010). "The proportion of positively stained MCM4 in tumor cell nuclei was ranging from 0.0 to 84.8% (median value 40.7%)." (PMID 20398247, 2010). "Therefore, MCM4 has been identified as a potential therapeutic target and prognostic marker in GBM, with reported associations to immune regulation, tumor progression, and drug sensitivity." (PMID 40565099, 2025). "Additionally, MCM4 expression significantly increased with tumor progression in both the GSE46517 and GSE98394 datasets." (PMID 40959096, 2025). "Similarly, TCGA LUAD data revealed that MCM4 mRNA levels were significantly higher in tumor tissues, particularly in advanced-stage (Stage II–IV) compared to early-stage (Stage I) samples." (PMID 40564876, 2025). "In the yellow cluster, cell cycle regulators such as CCNE2, MYBL2, and MCM4 were strongly suppressed in the combination, confirming that this approach induced cell cycle arrest and exerted a stronger inhibition of tumor cell proliferation compared to either treatment alone." (PMID 40753072, 2025). "Our analysis revealed that MCM4 expression was significantly elevated in tumor tissues." (PMID 40959096, 2025).
tumor (continued). "Similarly, the drug GW-3965, which has shown sensitivity in patients with high MCM4 expression, demonstrated strong inhibition of tumor growth and metastasis in mice." (PMID 40959096, 2025). "This tumor heterogeneity can lead to diverse expression patterns of MCM4, which may be regulated differently based on the tumor microenvironment, genetic mutations, or epigenetic factors." (PMID 40959096, 2025). "Additionally, MCM4 expression was positively correlated with various matrix metalloproteinases, supporting its role in promoting tumor invasiveness." (PMID 40564876, 2025). "A cut-off of > 75% positive tumor cells was selected for MCM4 among the AC cases in the OS analysis (log rank p-value 0.0005), which resulted in 15 cases (12%) identified as having a high MCM4 expression." (PMID 40333815, 2025). "Correlation heatmap revealed that MCM4 expression was positively associated with tumor cells, while exhibiting a significant negative correlation with immune cells such as CD4+ T cells and CD8+ T cells." (PMID 40959096, 2025). "The recruitment of myeloid-derived suppressor cells (MDSCs) is promoted, while there is a negative correlation with natural killer T (NKT) cells, suggesting that MCM4 may play a role in modulating the tumor microenvironment and mechanisms of immune evasion." (PMID 40230453, 2025). "MCM4 expression was predominantly found in tumor cells and proliferating T cells." (PMID 40959096, 2025). "For example, gene module 9, containing the genes TOP2A and MCM4, correlated with resection/tumor grade and was mainly expressed by G1/S/G2/M tumor cells, providing support for the existing notion that higher-grade tumors contain larger proportions of proliferating malignant cells." (PMID 39880824, 2025). "We further observed a decrease in GPX4 levels in tumor samples with MCM4 knockdown." (PMID 39290263, 2024). "Moreover, there was a significant reduction in GSH levels in MCM4-silenced tumor samples, while ROS and MDA levels were elevated after MCM4 knockdown." (PMID 39290263, 2024). "The tumor size was significantly reduced in the MCM4-silenced group." (PMID 39290263, 2024). "The overexpression of MCM4 may lead to aberrations in the cell cycle, promoting uncontrolled cell proliferation, thus accelerating tumor growth and metastasis." (PMID 38499612, 2024). "In vivo, knockdown of MCM4 attenuated tumour growth in xenograft mouse model." (PMID 37817427, 2023). "Although we showed that MCM4 could contribute to tumor progression in UTUC, the molecules with which MCM4 is associated remain unclear." (PMID 37737200, 2023). "When > 10% of tumor cells were stained, immunostaining was considered positive for MCM4." (PMID 37737200, 2023). "In vivo, knockdown of MCM4 inhibited tumour volume and weight in xenograft mouse model." (PMID 37817427, 2023). "This study found high expression of MCM4 in tumour samples in relative to normal control groups." (PMID 37817427, 2023). "Moreover, MCM4 expressed cells were frequently observed in the deeper invasive region compared to the surface of the tumor." (PMID 37737200, 2023). "The impact of MCM4 on tumor development has been widely reported." (PMID 35719366, 2022). "This suggests that aberrant expression of MCM4 in tumor tissue could affect DNA replication and further affect the occurrence, development, and prognosis of tumors." (PMID 35719366, 2022). "In addition, the expression of the MCM4 protein in lung adenocarcinoma tumors and paracancerous tissue was also examined by IHC, and the results indicated that MCM4 was significantly highly expressed in LUAD tumor tissues." (PMID 36291859, 2022). "Furthermore, the expression of MCM4 was significantly upregulated in human LUAD tumor tissues compared with normal controls, and higher expression of MCM4 predicted poor prognosis in LUAD patients." (PMID 35790743, 2022).